EPAS1 (endothelial PAS domain protein 1)
Diseases named in the same sentence as EPAS1 in open-access papers (continued):
Sharing a sentence is not in itself a finding about the gene and the disease.
cancer (495 papers, 2004 to 2026). A tumor composed of atypical neoplastic, often pleomorphic cells that invade other tissues. "Ubiquitin carboxyl-terminal hydrolase 33 (USP33) is an essential deubiquitinase that stabilizes the HIF-2a protein (encoded by the Epas1 gene) via the ERK1/2-dependent mechanism to promote a hypoxia response in cancer cells." (PMID 41009560, 2025). "Focal adhesion, cAMP signaling pathways, and pathways in cancer were also under the most upregulated KEGG pathways in PPGLs with EPAS1 mutation compared with tumors bearing a mutation in one of the cluster 2 susceptibility genes (NF1, RET, MAX)." (PMID 35159368, 2022). "While several studies have revealed that HIF2α has been implicated in cancer, the specific physiological functions of EPAS1 are not yet fully understood." (PMID 25569234, 2015). "To date, there are no reports on Sp1-mediated regulation of the EPAS1 gene, which encodes HIF-2α, in cancer cells." (PMID 26703734, 2015). "Interestingly, EPAS1 expression was the first under the cut-off line and, therefore, would not exclude this gene as being of minor importance in the susceptibility to cancer." (PMID 39888575, 2026). "Similarly, mutation‐positive CRC tissues had shown notable EPAS1 mRNA overexpression in comparison to those of non‐mutated cancer samples." (PMID 34250767, 2021). "High expression of EPAS1 was associated with the progression of other types of cancer." (PMID 34828399, 2021). "Moreover, since there is significant ethnic variation of many of these EPAS1 variants in non-cancer gnomAD, we confined statistical comparison to our PPGL cases against European non-Finnish controls (i.e. the relevant ethnic background for our cases)." (PMID 33300499, 2021). "EPAS1 has been associated with various cancer types and other diseases." (PMID 34828399, 2021). "In addition, we analysed EPAS1, also known as HIF-2A, a transcription factor that responds to hypoxia, a hallmark of cancer." (PMID 32543350, 2020). "In conclusion, the genetic polymorphism of the EPAS1 gene may lead to variation of its gene expression levels to drive progression of the cancer and serve as a prognostic marker for NSCLC." (PMID 26263511, 2015). "However, EPAS1 has a key function in the cellular response to low oxygen, and there has been a growing emphasis on its role in transcriptional activation, especially in association with cancer." (PMID 34828399, 2021). "The same analysis pointed to EPAS1 as a member of a significant network belonging to the Pathways in cancer, a complex group of biological functions such as those involved in Ras, MAPK, VEGF, and HIF-1 signalling cascades (Kanehisa and Goto, 2000)." (PMID 39513938, 2024). "Four of these loci composed the gene network overall ascribable to the Pathways in Cancer biological functions, which included also the EPAS1 positive control for AI." (PMID 39513938, 2024). "EPAS1, an oncogene which is overexpressed in cancer cells in response to hypoxic conditions, serves as a proangiogenic factor in contrast to sorafenib which has anti-angiogenic activity." (PMID 38789983, 2024). "Meta-analysis data from six randomized phase III trials in different cancers, including BC, suggested that variants in VEGF-A and EPAS1 are potential predictors of bevacizumab (anti-VEGF monoclonal antibody treatment) outcome." (PMID 37447165, 2023). "In selected vertebrate cell types or in cancer cells, another O2-sensitive subunit, EPAS1/HIF2A is also expressed." (PMID 38276269, 2023). "In particular, HIF1A and EPAS1/HIF2A can have opposing effects in cancer cells by controlling the transcription of different target genes." (PMID 38276269, 2023). "Analyzing the GOI expression when subgroups were based on the Youden’s J statistic for age, we observed significantly elevated levels of both HIF1A (p = 0.0023) and EPAS1 (p = 0.0246) between controls and cancer patients in the group > 56 yrs." (PMID 36230822, 2022).
cancer (continued). "Current research has also found that SIPA1 protein can prove breast cancer cell stemness by targeting the CD44 gene, and enhance aerobic glycolysis of cancer cells by targeting the EPAS1 gene to promote cancer cell metastasis." (PMID 36230738, 2022). "Hypoxia-induced transcription factors (HIFs) including HIF-2α (also known as EPAS1) play important roles in regulating cancer cell stemness by activating multiple transcriptional programs under hypoxia." (PMID 35301432, 2022). "We presented the top 30 correlations between CTRP drug sensitivity and mRNA expression of ACSL3 and EPAS1 in pan cancer, as well as the correlation between GDSC drug sensitivity and mRNA expression of ACSL3 and EPAS1 in pan cancer." (PMID 35223835, 2022). "The HIF1A and EPAS1 expression levels were higher in benign lesions compared to malignant tumors (p = 0.04067 and p = 0.0228, respectively)." (PMID 36230822, 2022). "The obvious molecular mechanism for EPAS1 induction in cancer is intratumoral hypoxia, but also genetic alterations." (PMID 34828399, 2021). "EPAS1 overexpression is an obvious finding in cancer and can enhance cancer metastasis via EMT induction." (PMID 34943856, 2021). "The majority of available studies regarding EPAS1 downstream transcriptional activity and its upstream regulation were performed on cancer cell lines and tissues, thus the enrolment of the regulatory mechanisms in healthy tissue must be carefully considered." (PMID 34828399, 2021). "Amplification of DNA copy number (63.4%; n = 52/82) followed by mRNA overexpression (72%; n = 59/82) of EPAS1 tissues implies its cancer‐promoting properties in patients with CRC." (PMID 34250767, 2021). "In vitro and in vivo experiments demonstrated that EPAS1 down-regulation in PC cells due to targeted delivery, resulted in a reduction in cancer proliferation and the number of microvessels." (PMID 34943856, 2021). "In CRC, 63.4% (n = 52/82) of cancer tissue samples showed EPAS1 copy number amplification, whereas 18.3% (n = 15/82) exhibited EPAS1 DNA deletion when compared to the matched non‐cancer tissues." (PMID 34250767, 2021). "Expression of EPAS1 mRNA in cancer was significantly (p < 0.001) higher when compared to that in matched non‐cancer tissues (0.83 ± 0.05 vs. 0.76 ± 0.06)." (PMID 34250767, 2021). "Several studies also noted higher or lowered expression of EPAS1 both in mRNA and protein levels in patients with other cancers." (PMID 33042797, 2020). "Endothelial PAS domain-containing protein 1 (EPAS1) is an oxygen-sensitive component of the hypoxia-inducible factors (HIFs) having reported implications in many cancers by inducing a pseudo-hypoxic microenvironment." (PMID 33114456, 2020). "Stabilizing HIF1A by hypoxia or cobalt chloride inhibits ferroptosis, whereas endothelial PAS domain protein 1 (EPAS1/HIF2A) promotes ferroptosis in certain cancer cells." (PMID 33117818, 2020). "The distribution of EPAS1 mRNA expression in cancer tissues was significantly (1.656 ± 0.193 vs. 0.573 ± 0.078; p < 0.05) higher when compared with nonneoplastic tissue samples." (PMID 33042797, 2020). "These identified CMT DMRs were found in CpG islands in the 21st and 1st introns of ANK2 and EPAS1, respectively, and the increase in methylation in the cancer samples are shown via linear mixed model (LMM) with thresholds of both 10% and 5%." (PMID 33218035, 2020). "For example, docetaxel, a chemotherapy medication used to treat many types of cancer, negatively correlates with EPAS1 expression." (PMID 33299416, 2020). "We found that both HIF‐1α and HIF‐2α (EPAS1) have the ability to activate oncogenes deeply involved in cancer biology, such as VEGF, CXCL8 and PGR." (PMID 32537867, 2020). "The four remaining transcription factors retrieved as potential MRs—DACH1, EPAS1, FOXA2, and FOXM1—have been extensively reported in associations with cancers in literature." (PMID 31503425, 2019).
cancer (continued). "An example of a cancer phenotype that displays experimental context-specificity is the role of hypoxia-inducible factor 2 (HIF2A), encoded by the EPAS1 gene, as a driver of renal tumorigenesis." (PMID 30104738, 2018). "For example, the gene with the largest value of jGRP, EPAS1, plays important roles in cancer progression and has been widely reported to be over-expressed in non-small cell lung cancer (NSCLC) tissues as a significant marker for poor prognosis." (PMID 28830341, 2017). "In order to explorer effects of the rs13419896 SNP on endogenous gene expression levels of the EPAS1, we genotyped the SNP and evaluated levels of the gene expression in diverse cancer cell lines." (PMID 26263511, 2015). "This was also supported by the observation of gene and protein expression levels of EPAS1 by the rs13419896 SNP in various cancer cells." (PMID 26263511, 2015). "Several lines of evidencehave indicated that EPAS1 is related to multiple aspects of cancers, including cell proliferation, angiogenesis, apoptosis, metabolism, metastasis and resistance to chemotherapy." (PMID 26587830, 2015). "Among the numerous targets predicted, 2 genes, namely, PTPRU and EPAS1,were previously reported to be involvedin cancer metastasis." (PMID 26587830, 2015). "Primarily, we analyzed the molecular factors, such as HIF1A, EPAS1, and VEGFA gene expression levels, that could influence cancer risk and development." (PMID 39888575, 2026). "Furthermore, verifying Epas1 decrease in CD8 T cells in cancer patients is helpful to explore the therapeutic potential of Epas1 overexpression in ACT with aged CD8 T cells." (PMID 39925817, 2025). "The availability and application of proven EPAS1-inhibitors, like Belzutifan, for treatment of specific cancer types may promote the usage of these drugs for BPDCN and ALCL as well." (PMID 38474011, 2024). "There is growing evidence showing that EPAS1 is related with cancer initiation and progression." (PMID 37124944, 2023). "Along this process, miR-21 and the cancer-involved pathways were contacted via EPAS1." (PMID 35486636, 2022). "The structure, function, hypoxic response, spatiotemporal dynamics, and roles in the progression and persistence of cancer of this HIF-2α molecule and its EPAS1 gene are highlighted in this review, alongside a discussion of current therapeutics and future directions." (PMID 35267567, 2022). "Additionally, EPAS1 expression was elevated in cancer patients with ≤29 BMI compared to BMI > 29 (p = 0.0118)." (PMID 36230822, 2022). "Moreover, patients with tumors harboring EPAS1-expressing TAMs were characterized by shorter cancer-specific survival." (PMID 36421334, 2022). "In addition, higher frequency (more than 75%) of cancers of T‐stages one to three exhibited high EPAS1 mRNA expression, while only 43% of cancers of T‐stage four showed high EPAS1 mRNA expression (p = 0.01)." (PMID 34250767, 2021). "Endothelial PAS domain‐containing protein 1 (EPAS1) has implications in many cancers." (PMID 34250767, 2021). "Our results and available information in the literature implied that EPAS1 could be a potential target for developing effective therapeutics for better management of patients with cancer." (PMID 33042797, 2020). "Similarly, the mRNA expression of EPAS1 cancer cells (KYSE70, KYSE450, and HKESC-1) is significantly higher (1.98 ± 0.09, 2.24 ± 0.11, 2.45 ± 0.12, respectively) than noncancerous HaCaT (1.2 ± 0.06) cells." (PMID 33042797, 2020). "Some HIFs, such as HIF1A, ARNT, EPAS1, and HIF3A, were linked with unfavorable outcomes for pan-cancer, while two HIFs including ARNTL and ARNT2 were associated with favorable outcomes in pan-cancer." (PMID 33299416, 2020).
cancer (continued). "Apart from being involved in the cancer progression, low levels of DNMT3a could result in an unscheduled activation of EPAS1 gene which contributes to cell survival under extreme hypoxic conditions." (PMID 28393842, 2017). "In fact, we found that a fragment in the intron 1 of EPAS1 contains transcriptional regulatory elements and nucleotide difference at the rs13419896 locus may functionally affect enhancer activities in cancer cell lines." (PMID 26263511, 2015). "Moreover, between distinguished age groups, cancer cases differed in EPAS1 and HIF1A." (PMID 36230822, 2022). "Interestingly, 65.7% (n = 44/67) of cancers from patients born in Australia or New Zealand showed EPAS1 mRNA overexpression, whereas 93.3% (n = 14/15) of cancers from patients born overseas exhibited EPAS1 mRNA overexpression (p = 0.02)." (PMID 34250767, 2021). "Therefore, therapeutic strategies silencing EPAS1 could act as a management strategy for controlling cancer cell growth and metastasis in patients with CRC." (PMID 34250767, 2021). "Thus, the therapeutic strategies targeting EPAS1 could have the potential for effective inhibition of cancer cell growth, migration, and invasion." (PMID 33042797, 2020). "When the cells were divided into two groups by presence or absence of the A allele at the rs13419896 locus, cancer cells with the A allele of the rs13419896 demonstrated significantly higher EPAS1 gene expression levels than for any others without the A allele (P = 0.022, Welch’s t test)." (PMID 26263511, 2015). "In cancer-affected tissue, significant correlations of VEGFA with HIF1A and EPAS1 were weak and only in post-menopausal cases." (PMID 39888575, 2026). "22d also showed a significant downregulation of HIF-1α, EPAS-1(HIF-2α), and carbonic anhydrase IX (CA-IX), all proteins involvedin several hallmarks of cancer." (PMID 38261767, 2024). "One basic feature of physiological processes and pathophysiological conditions such as cancer and ischaemic diseases is hypoxia, and the main regulators of adaptive response to hypoxia are HIF‐1αand EPAS1(EPAS1)." (PMID 38722283, 2024). "Injury-induced populations were highest for TFs related to cell proliferation, self-renewal, and cancer involving both intrinsic (E2F family, MYC, and ZFX) and extrinsic (HIF1a, EPAS1/HIF2a, NFYB, LEF1, GLI2, VDR, and SMAD1/3/5) pathways." (PMID 38905342, 2024). "Researchers have elucidated the complex regulatory relationship between EPAS1 and PI3K/AKT signaling pathway in different cancers, in which factors such as PTEN, YY1, SCD1, and CD44 also play important roles." (PMID 37124944, 2023). "Over the past years, HIF1A, EPAS1, and VEGFA have been highlighted to be attractive potential targets for anti-cancer therapies." (PMID 36230822, 2022). "We found that expression of HIF1A and EPAS1 was higher in controls and VEGFA higher in patients with malignant tumors." (PMID 36230822, 2022). "In particular, cluster 11 had high expression levels of cancer stem cell (CSC) marker genes, including NOTCH1, KLF4, CD44, EPAS1, and MYC." (PMID 36618022, 2022). "The corresponding heatmap data among pan-cancer show a positive correlation between ABCG2 and EPAS1, and GCLC in most cancer types." (PMID 36555598, 2022). "We showed EPAS1 elevated level in controls and VEGFA in malignant tumors, but only in the group with a lower number of comorbidities." (PMID 36230822, 2022). "LINC01436 advances cancer growth and metastasis in vivo, and LINC01436 can exhibit its function by sponging miR-30a-3p that directly regulates HIF-2α (also known as endothelial PAS domain-containing protein 1 (EPAS1))." (PMID 34298879, 2021). "OC-X treatments also caused surge upregulation of several important biomarkers within each cancer progression stage, including UCP1, NOSTRIN, SCGB3A1, ENG, EPAS1, SFTPD, and BMP4." (PMID 34069906, 2021). "A human cancer cell study has shown that HIF1A and EPAS1 transcriptional response to hypoxia varies among human cells." (PMID 34724959, 2021).
cancer (continued). "Among them, HIF3A and EPAS1 are significantly downregulated, whereas ATNTL and ARNT2 show minimal expression changes in most cancer types." (PMID 33299416, 2020). "EPAS1 DNA numbers (1.4 ± 0.07, 2.10 ± 0.10, 2.41 ± 0.12) in ESCC cancer cell lines KYSE70, KYSE450 and HKESC-1, respectively, are higher when compared with that of nonneoplastic keratinocyte HaCaT (1.01 ± 0.05) cells." (PMID 33042797, 2020). "The genes that were shared by three different cancers (i.e., FGFR3, EPAS1, SRC, and FOXD3) are shown in coral, and the genes that were shared by two types of cancers (i.e., PPARG, FOXO1, CDK4, NKX3-1, PIK3R1, PRKCB and EDNRB) are shown in light pink." (PMID 28178311, 2017). "Hypoxia-inducible factor-2α (HIF-2α, or EPAS1) is important for cancer progression, and is a putative biomarker for poor prognosis for non-small cell lung cancer (NSCLC)." (PMID 26263511, 2015). "No up-regulated genes, but four down-regulated genes (COL4A1, COL4A2, EPAS1 and FGF15) of the "Pathways in cancer" were found in both cell lines." (PMID 25992885, 2015). "As results, EPAS1 proteins were detected in PC9 and LC-KJ with the A allels even under normoxic conditions and were obviously increased in some of hypoxic cancer cells, A549, PC9, LC-KJ, and LC-S." (PMID 26263511, 2015). "Thus, EPAS-1 could be a novel target for cancer therapeutics." (PMID 25192290, 2014). "Additionally, significantly higher expression was observed between groups distinguished by Youden’s J cut-off points for age, in the cancer group, for HIF1A (p = 0.0398) and EPAS1 (p = 0.0022)." (PMID 36230822, 2022). "In these 11 cancer types, NPM1 expression is positively correlated with expression of HIF1A but not with EPAS1 which encodes HIF‐2α, in line with our data showing that NPM1 interacts only with the HIF‐1α isoform." (PMID 34388291, 2021). "In CMT tissue, our study of EPAS1 and its indications of hypermethylation in cancer as opposed to normal remains a novel and intriguing finding and highlights this target as a candidate tissue biomarker for CMT." (PMID 33218035, 2020). "Therefore, the results of this study will enrich the current understanding of EPAS1 in directing carcinogenesis of ESCC, as well as opening new opportunities for the development of novel therapeutic strategies against cancer." (PMID 33042797, 2020). "A significantly higher EPAS1 DNA expression was noted in cancer samples (1.706 ± 0.209) when compared with noncancerous (0.569 ± 0.078) samples." (PMID 33042797, 2020). "With the obtained information we hypothesized that EPAS-1 participates in FBI-1 related tumorigenesis and cancer development." (PMID 25192290, 2014). "Although EPAS-1, as a novel tumorigenesis player, has been investigated for several years regarding its role in hypoxia response of cancer cells, the mechanism it exerts in cancer development has not been demonstrated well." (PMID 25192290, 2014). "Only EPAS1 was weakly correlated with age in controls but not cancer patients." (PMID 39888575, 2026). "Importantly, EPAS1 mRNA overexpression was noted more often in cancers without pre‐operative chemo‐radiotherapy (73.7% vs. 33.3%)." (PMID 34250767, 2021). "In addition, 100% (n = 10/10) of CRC with cancer perforation showed no mutations in EPAS1 sequence, whereas 18% (n = 13/82) of CRC without mutations in EPAS1 had cancer perforation (p = 0.05)." (PMID 34250767, 2021). "In addition, the mRNA expression ratio of EPAS1 was significantly higher in cancer in comparison to those in noncancer tissue samples (1.656 ± 0.12 vs. 0.573 ± 0.07; p < 0.001)." (PMID 33042797, 2020). "The results showed that apart from EPAS1 and RAD51AP1 that without immunohistochemistry data, SQLE, CAPG, RRM2, SLC1A5, and SRC as dangerous genes were higher expressed in cancer tissues." (PMID 37461802, 2023). "As a result of that and the lack of cancer specificity in the targeting of hypoxic response, no selective inhibitors of HIF1A/EPAS1 are currently clinically approved." (PMID 32413951, 2020).